CTNNB1 (catenin beta 1)
Diseases named in the same sentence as CTNNB1 in open-access papers (continued):
Sharing a sentence is not in itself a finding about the gene and the disease.
Hypertension (8 papers, 2016 to 2025). The presence of chronic increased pressure in the systemic arterial system. "The duration of hypertension is shorter among CTNNB1 mutation carriers than KCNJ5 mutation carriers or WT APA patients (all p < 0.001)." (PMID 28102204, 2017). "Of great interest, we found that patients who harbor CTNNB1 mutations had a higher likelihood of residual hypertension after adrenalectomy, when compared with wild-type APA patients or KNCJ5 mutation carriers." (PMID 28102204, 2017). "Even after adjustment for possible variables when compared with all those who had KCNJ5 mutations, being a CTNNB1 mutation carrier was an independent factor to predict post-operative residual hypertension [odds ratio (OR) = 18.9, p = 0.010]." (PMID 28102204, 2017). "Although CTNNB1 mutation carriers had a shorter duration of hypertension, their average age was higher than the other groups." (PMID 28102204, 2017). "Compared with the KCNJ5 mutation carriers (12.5% vs. 79.3%, p < 0.001) and WT group (12.5% vs. 57.3%, p = 0.018), the CTNNB1 mutation carriers had a much lower chance of recovery from hypertension even after one-year follow-up." (PMID 28102204, 2017). "After adrenalectomy, CTNNB1 mutation carriers had a higher possibility (87.5%) of residual hypertension than other APA patients." (PMID 28102204, 2017). "Patients with APAs harboring CTNNB1 mutations were older and had shorter duration of hypertension." (PMID 28102204, 2017). "One of the possible explanations of the higher post-adrenalectomy residual hypertension among the patients who harbor CTNNB1 mutations could be that age-related essential hypertension played an important role in hypertension observed for these patients." (PMID 28102204, 2017). "However, after matching for the effects of age, sex and blood pressure, APA patients who had CTNNB1 mutations had significantly higher risk of post-operative residual hypertension than either KCNJ5-mutaion carriers (OR = 18.2, p = 0.046) or WT patients (OR = 14.5, p = 0.028)." (PMID 28102204, 2017). "APAs carrying CTNNB1 mutations have been previously reported to have a higher possibility of residual hypertension than other mutant APAs, albeit these were most likely single CTNNB1 mutant APAs." (PMID 40557039, 2025). "Complete cure of hypertension, on removal of CTNNB1-mutant APAs, may be predicted through unilateral detection of secreted proteins such as NPNT during adrenal vein sampling." (PMID 28416583, 2017). "In summary, we described CTNNB1 somatic mutation prevalence among our APA patients, along with its phenotype and clinical outcomes, and identified a female gender dominance and higher risk for post-adrenalectomy residual hypertension." (PMID 28102204, 2017). "However, both patients harboring the CTNNB1 mutations were >50 years old, and thus, age-related essential hypertension cannot be ruled out for the post-adrenalectomy residual hypertension seen." (PMID 40557039, 2025). "Furthermore, the tumor size and ratio of parental hypertension were not significantly different among patients who had CTNNB1 mutations, KCNJ5 mutations or WT." (PMID 28102204, 2017). "Of particular note, one of the 16 cases in Zhou’s study had the same combination of mutations as our case (CTNNB1 p.D32Y and GNA11 p.Q209H) and the patient had no history of hypertension during her past 10 pregnancies." (PMID 38505749, 2024). "When the CTNNB1 mutation carriers were compared with all WT APA patients, the chance of having residual hypertension was not significant (p = 0.051)." (PMID 28102204, 2017). "Clinically, both patients with a CTNNB1 and CACNA1D double mutant APAs and the single CTNNB1 mutant APAs have not achieved complete post-adrenalectomy resolution of hypertension." (PMID 40557039, 2025).
non-small cell lung carcinoma (8 papers, 2018 to 2024). A group of at least three distinct histological types of lung cancer, including non-small cell squamous cell carcinoma, adenocarcinoma, and large cell carcinoma. "CTNNB1 was found to be associated with 21 pathways, among which the ‘Non-small cell lung cancer’ pathway was significantly suppressed." (PMID 39062881, 2024). "Oncogenic mutations in CTNNB1, most frequently missense mutations in exon 3, have been recurrently identified in liver, and uterine cancers, and in a small subset of non-small cell lung cancers (NSCLCs)." (PMID 37347751, 2023). "One re-biopsy sample showed an activating CTNNB1 mutation, which is reported to confer resistance to EGFR therapies in non-small cell lung cancer." (PMID 32397977, 2020).
ovarian tumor (8 papers, 2003 to 2025). "Finding identical MLH1 and CTNNB1 variants would suggest a clonal relation between the colon and ovarian tumor." (PMID 29124495, 2018). "Tissue-specific differences for expression of selected β-catenin/TCF-regulated genes, such as Myc, may contribute to the context-dependent effects of Ctnnb1 gene dosage in Apc mutation-driven colon and ovarian tumors." (PMID 26528816, 2015). "In contrast, the somatic mutations in CTNNB1 and PIK3CA were detected not only in the endometrial and ovarian tumours, but also in the lung metastasis." (PMID 28103826, 2017). "We have recently reported that aberrant WNT7A is observed in serous ovarian carcinomas, and WNT7A is the sole ligand accelerating ovarian tumor progression through CTNNB1 (β-catenin)/TCF signaling in the absence of CTNNB1 mutations." (PMID 27195958, 2016). "In OC, KRAS was downregulated, whereas the other hub genes CTNNB1, BRCA1, and JUN were upregulated in ovarian tumor tissues." (PMID 41186627, 2025).
renal carcinoma (8 papers, 2015 to 2024). A carcinoma arising from the epithelium of the renal parenchyma or the renal pelvis. "Interestingly, no significant change was observed in the expression of HES1, GLI1 and NANOG, whereas the expression of CTNNB1 was markedly increased, suggesting that CTNNB1 may be involved in increased renal cancer stem-like phenotype caused by the down-expression of PIK3R1." (PMID 25757764, 2015). "In present study, the depletion of CTNNB1 in renal cancer cells decreased the cancer stem-like phenotype of these cells." (PMID 25757764, 2015). "Similarly, miR-1826 that is significantly downregulated in renal cancer tissues acts as tumor suppressor agent promoting apoptosis and cell cycle arrest by knockdown of CTNNB1 (beta-catenin) and MEK1 genes in VHL-inactivated ccRCC cells." (PMID 28326269, 2015). "Therefore, the PI3K/AKT and WNT/CTNNB1 pathway work together as a PI3K/AKT/GSK3β/CTNNB1 pathway which induces differentiated renal cancer cells to transform into a more cancer stem-like cells." (PMID 25757764, 2015). "Overall, PIK3R1 down-regulation in RCC promotes propagation, migration, EMT and stem-like phenotype in renal cancer cells through the AKT/GSK3β/CTNNB1 pathway, and may contribute to progression and metastasis of RCC." (PMID 25757764, 2015). "Therefore, in consistence with previous studies, our study suggests that the PI3K-AKT and WNT/CTNNB1 pathways converge on GSK3β in renal cancer cells." (PMID 25757764, 2015). "Cell experiments confirmed the inhibitory effects of increased GJA1 expression on the migratory capacity of human renal cancer (RCC) cell lines, and protein–protein interaction (PPI) analysis predicted that CDH1 and CTNNB1 were closely related to Cx43." (PMID 38792963, 2024). "Among different subgroups in renal cancer scRNAseq data, significant correlations between EMP1/COL3A1 and four EMT genes (VIM, SNAI2, TWIST1, and CTNNB1) were found in c9 fibroblasts." (PMID 38187400, 2023). "As a tumor suppressor in bladder and renal cancers, VEGFC, CTNNB1, and MAP2K1 were three targets of miR-1826 to mediate its inhibiting effect on tumorigenesis." (PMID 32104674, 2020). "The downregulation of PIK3R1 promotes EMT, migration, and cancer stem cell phenotype in renal cancer cells and may contribute to the progression and metastasis of RCC by activating the PI3K/AKT/GSK3β/CTNNB1 pathway." (PMID 25757764, 2015).
autism spectrum disorder (7 papers, 2017 to 2025). A spectrum of developmental disorders that includes autism, and Asperger syndrome. "For example, deletion of the gene encoding β-catenin (CTNNB1) in neurons was recently found to cause ASD-like behavior, and rare mutations have been identified in patients with learning defects and autism spectrum disorder (ASD)." (PMID 33424735, 2020).
cutaneous melanoma (7 papers, 2013 to 2022). A primary melanoma arising from atypical melanocytes in the skin. "We examined the prognostic significance of somatic APC/CTNNB1 mutations in the Cancer Genome Atlas Project for Skin Cutaneous Melanoma (TCGA-SKCM) database." (PMID 34986841, 2022). "To investigate whether the presence of somatic mutations in APC/CTNNB1 genes is a prognostic factor in cutaneous melanoma, we performed OS analysis on the TCGA SKCM cohort." (PMID 34986841, 2022).
endometrioid tumor (7 papers, 2012 to 2022). A benign, borderline, or malignant epithelial tumor of the female reproductive system characterized by the presence of glands and/or cysts lined by neoplastic cells that resemble endometrial cells. "We identified 21 different mutations in CTNNB1 in 88/454 (19%) endometrioid tumors." (PMID 22383975, 2012). "Other altered genes labelling the endometrioid cancer were CTNNB1, KRAS, POLE, and ARID1A genes, each of them accepted as genetic biomarker of the endometrioid tumors." (PMID 36010253, 2022).
esophageal cancer (7 papers, 2012 to 2023). A primary or metastatic malignant neoplasm involving the esophagus. "Mutations in the CTNNB1 gene promote the development of esophageal cancer by upregulating the Wnt/beta-catenin pathway and the downstream target genes." (PMID 37534256, 2023). "Decreased expression of CDH1 or CTNNB1 in the cell membranes of cancer cells is associated with poor survival of patients with esophageal cancer." (PMID 27600761, 2016). "We previously reported that the accumulation of CTNNB1 in the nucleus occurs infrequently in esophageal cancer." (PMID 27600761, 2016). "In this study, we found that the decreased expression of CDH1 or CTNNB1 in the cell membrane in cancer tissues accompanied the local progression and lymph node metastasis of esophageal cancer." (PMID 27600761, 2016). "Few mutations in CTNNB1 and APC occur in the setting of esophageal cancer." (PMID 27600761, 2016). "Both CDH1 and CTNNB1 were co-expressed in 22.1 % (19/86) of esophageal cancer tissues." (PMID 27600761, 2016). "However, the involvement of decreased expression of CTNNB1 at the cell membrane is unclear in metastasis, and the progression of esophageal cancer is unclear." (PMID 27600761, 2016). "On the contrary, miR-200a targets Catenin Beta 1 (CTNNB1), the member of the Wnt/β-catenin pathway, and promotes the invasion and migration of esophageal cancer cells." (PMID 36158660, 2022). "The results showed a significant correlation between the expression levels of SPINK5 and β‐catenin (CTNNB1), LRP5, LRP6, DVL3, LEF1, AXIN2, MYC, and cyclin D1 (CCND1) in esophageal cancer." (PMID 30868765, 2019). "Our data suggested that CDH alone or CTNNB1 alone did not affect the prognosis of the patients with esophageal cancer, though we could not clarify the discrepancy between their data and ours." (PMID 27600761, 2016). "While our results suggested that CDH1 or CTNNB1 expression alone did not affect the prognosis of patients, whether CDH1 and CTNNB1 expression may serve as a good prognostic marker in esophageal cancer is still controversial." (PMID 27600761, 2016).
hepatitis B (7 papers, 2011 to 2023). "The higher incidence of CTNNB1 mutations in this age group also suggests that they are less likely to have hepatitis B induced HCC." (PMID 29254188, 2017). "CTNNB1 mutations are more frequent in alcohol-related HCC and associated with old age and negatively associated with hepatitis B and elevated alpha-fetoprotein, thereby mirroring the etiologic profile of the northern European HCC population." (PMID 33827453, 2021).
hepatocellular adenoma (7 papers, 2016 to 2024). A benign epithelial neoplasm arising from the hepatocytes. "In addition, CTNNB1 mutation is identified in more than 10% hepatocellular adenoma (HCA), which is a benign liver neoplasm with risk of malignant transformation." (PMID 36122209, 2022). "However, 28% of all GSD patients diagnosed with hepatocellular adenoma display mutations in CTNNB1, which accelerate the metabolic phenotype and the malignant transformation towards HCC." (PMID 29541410, 2018). "Glutamine synthetase (GS) has been established as a useful immunohistological adjunct in the diagnostic procedure of hepatocellular adenoma (HCA) harboring CTNNB1 mutations, being more sensitive than b-catenin immunohistochemistry (IHC), to identify this subtype of HCA." (PMID 38453738, 2024). "Highly activating β-catenin with CTNNB1 mutation types is associated with malignant transformation and intense pattern of GS staining; However, weak mutations display more frequently for hepatocellular adenoma (HCA)." (PMID 37635935, 2023). "A modest correlation between CTNNB1 gene mutations and GLUL expression at the protein level determined by GS staining was also found in samples of hepatocellular adenoma and carcinoma." (PMID 34235580, 2021).
Lynch syndrome (7 papers, 2015 to 2025). An autosomal dominant hereditary neoplastic syndrome characterized by the development of colorectal carcinoma and a high risk of developing endometrial carcinoma, gastric carcinoma, ovarian carcinoma, renal pelvis carcinoma, and small intestinal carcinoma. "Further, recent data show that in Lynch syndrome-associated CRCs, biallelic mutations of CTNNB1 seem to be required to mediate an oncogenic driver effect, which we included in the definition of the gene mutation graphs." (PMID 34003820, 2021). "While APC mutations are found more frequently in microsatellite stable (MSS) CRCs, CTNNB1 mutations are commonly associated with microsatellite instability (MSI-H) particularly in cancers from Lynch syndrome patients." (PMID 33115416, 2020). "On the one hand, stabilizing homozygous CTNNB1 mutations play a crucial role, especially in human CRC associated with Lynch syndrome." (PMID 34885050, 2021). "NCI-H295R and CUACC1 are steroid-producing and have mutations in the β-catenin gene (CTNNB1), while CUACC2 is a steroid-nonproducing cell line established from a patient with Lynch syndrome." (PMID 38451783, 2024).
prostate tumors (7 papers, 2016 to 2023). "Regarding EMT drivers, both SCAND1 and MZF1 expression negatively correlated with CTNNB1 expression in prostate tumor specimens." (PMID 36552758, 2022). "Compared to the normal prostate tissues or primary prostate tumors, the mRNA levels of DVL3, MAPK9, and CTNNB1 are higher in metastatic prostate tumors while the mRNA level of ROR2 is lower in metastatic prostate tumors." (PMID 27191743, 2016). "Gene expression of FZD5, DVL3, RELA, MAPK9, CTNNB1, and SNAI1 is higher in metastatic prostate tumors as compared to primary prostate tumors." (PMID 27191743, 2016). "Analysis of RNA-seq data showed that Ctnnb1 mRNA was upregulated in prostate tumors of Pb-T2-ERG;Trp53pcR172H/- mice, but not in prostatic tissues of Pb-T2-ERG and Trp53pcR172H/- single mutant mice relative to WT mice, and this observation was further confirmed by RT-qPCR." (PMID 37537199, 2023). "In particular, we found primarily overexpression of CTNNB1, CDH1, SMAD2, SMAD3, TCF3, LEF1 in younger patients and overexpression of SNAI1 and underexpression of KRT5, KRT19, OCLN, CDH2 and MUC1 which clearly indicates different characteristics of prostate tumor in younger vs older patients." (PMID 29206234, 2017).
stomach cancer (7 papers, 2016 to 2025). "For instance, SNHG10 promotes the growth and migration of gastric tumors by targeting the miR-495-3p/CTNNB1 axis, activating the WNT pathway and the DDX54-mediated PBX3 feedback pathway." (PMID 36871072, 2023).
adrenal adenomas (6 papers, 2016 to 2024). "Although studies suggested that mutations in CTNNB1 are more common in inactive adrenal adenomas, they have also often been reported in cortisol-producing adrenal adenomas." (PMID 34489873, 2021). "Exome sequencing excluded a causative germline mutation but showed somatic mutations of the β-catenin protein gene (CTNNB1) in the adrenal adenoma, and of both the ubiquitin specific peptidase 8 (USP8) and the glucocorticoid receptor (NR3C1) genes in the pituitary adenoma." (PMID 34489873, 2021). "Moreover, as previously reported, a CTNNB1-mutation is associated with larger tumors, explaining the size greater than 40 mm of the adrenal adenoma in our case." (PMID 34489873, 2021). "Similarly, CTNNB1 mutations are observed in 70% of adrenocortical adenomas; however, the majority are non-secreting adrenocortical adenomas (61%), with a few cases of subclinical Cushing’s disease (22%) and overt Cushing’s disease (16%)." (PMID 39518893, 2024). "Activating mutations in CTNNB1 are more frequent in nonsecreting adrenal adenomas." (PMID 32783015, 2020). "Somatic mutations in the gene encoding beta-catenin (CTNNB1) have primarily been found in non-secreting adrenocortical adenomas, and there is some evidence that increased endocrine activity may be linked to aberrant cAMP signaling." (PMID 27512387, 2016). "Activation of the Wnt/beta-catenin pathway was also reported in around 40% of adrenocortical adenomas without any somatic mutation of PRKAR1A, most of them being explained by the occurrence of a somatic-activating mutation of the beta-catenin gene (CTNNB1)." (PMID 32783015, 2020).
alcohol (6 papers, 2018 to 2025). "We found that mutations in CTNNB1 were more likely to be identified in patients with alcoholic cirrhosis, which is consistent with the previous reports of association of CTNNB1 mutation with alcoholism." (PMID 34299031, 2021). "Furthermore, it has been reported that NASH‐HCCs were enriched in the Wnt/TGF‐beta class and displayed a significantly lower prevalence of the CTNNB1 molecular subclass compared with viral/alcohol‐HCCs." (PMID 35064579, 2022). "On the contrary, the HCV and alcohol‐related HCC exhibit a nonproliferation phenotype with moderately‐to‐well differentiation, lower serum AFP levels, and higher CTNNB1 and TERT promoter mutation." (PMID 40948427, 2025).